LEPR (leptin receptor)
Diseases named in the same sentence as LEPR in open-access papers (continued):
Sharing a sentence is not in itself a finding about the gene and the disease.
diabetes (205 papers, 2009 to 2025). "For instance, in this study, db/db mice (featuring a leptin receptor spontaneous mutation) were utilized to simulate a diabetes model." (PMID 40405912, 2025). "Polymorphisms of the leptin receptor (LEPR) gene are associated with type 2 diabetes mellitus (T2DM), but the association varies among different geographic populations." (PMID 40551902, 2025). "In contrast, the C57BL/KsJ-db/db mouse model spontaneously develops type 2 diabetic mellitus (T2DM) due to a mutation in the leptin receptor." (PMID 38448948, 2024). "Their efficacy was estimated in the treatment of sepsis, and pneumonia models in BALB/c mice, diabetes-associated wound infection in the leptin receptor-deficient db/db mice and infected burn wounds in rats." (PMID 39044206, 2024). "Leptin receptor-deficient db/db mice are a widely used animal model to study diabetes and its complications." (PMID 39375536, 2024). "β-cell specific PTEN-knockout mice were reported to have increased insulin signaling in β-cells and were protected against glucose intolerance induced by high fat diet and diabetes induced by leptin receptor deficiency or streptozotocin." (PMID 38578954, 2024). "Db/db mice have gene-encoding mutations at the leptin receptor, with high susceptibility to obesity and type 2 diabetes mellitus, and hence are suitable for the study of type 2 diabetes mellitus and metabolic liver and kidney disease." (PMID 39301568, 2024). "In previous studies our group has reported that TAC accelerates the transition from pre-diabetes to diabetes in a genotypic model of leptin receptor-deficient obese Zucker rats." (PMID 38745946, 2024). "In this study, the therapeutic effects of C. quadrangularis extract (CQR-300) on type 2 diabetes mellitus (T2DM) were investigated in a leptin receptor-mutated db/db mouse model." (PMID 39050759, 2024). "Previously, we observed an improvement in LTP deficits in mouse model of diabetes (leptin receptor deficient db/db) following administration of rosiglitazone via ICV and not by oral delivery." (PMID 37190025, 2023). "As the fields of genetics and diabetes research progress, we have an opportunity to gain a deeper understanding of how the LEPR gene, along with other genetic factors, impacts the risk of T2DM onset." (PMID 38198642, 2023). "To investigate the pathology of diabetes-related osteoporosis, we take the advantage of leptin-receptor-deficient mice (db/db), a mouse model for T2DM, to analyze bone phenotype." (PMID 37124755, 2023). "Our result is consistent with a prior observation that overexpression of CDK4-R24C under the insulin promoter rescued diabetes due to leptin receptor deficiency." (PMID 37712417, 2023). "In a few reported studies, induction of diabetes was based on the combination of STZ with a high-fat diet (STZ/HFD) or carried out on genetically modified animals with diabetes (leptin receptor-deficient (Leprdb/JNju, db/db) mice)." (PMID 36678910, 2023). "The most widely utilized animal model of diabetes is Leprdb/db mice, which have a leptin receptor mutation and represent an excellent animal model of diabetic complications." (PMID 36406423, 2022). "There are several animal models that can be used for the study of diabetes, both with gene deficiency (e.g., db/db mice with leptin receptor deficiency) and by induction of diabetes by drug administration (e.g., streptozocin)." (PMID 35336776, 2022). "Leptin receptor-deficient db/db mice were used to model a type 2 diabetes mellitus (T2DM) model in our study." (PMID 35941186, 2022). "Leptin is encoded by the obese gene (ob) and the leptin receptor by the diabetes gene (db) in mammals." (PMID 35454105, 2022). "We also found that Igf2bp2 trends lower in adipocytes of leptin-deficient (ob/ob) and leptin receptor-deficient (db/db) obese mice, which model diabetes onset and progression." (PMID 35036870, 2022). "Similar results were also observed in the leptin receptor-deficient db/db mice, a genetic mouse model for diabetes." (PMID 34335967, 2021).
diabetes (continued). "Leptin receptors are encoded by the diabetes (db) gene and by the leptin receptor gene, which can produce six different isoforms: ObRa-f." (PMID 34827650, 2021). "Leptin receptor deficient db/db mice are mature animal models of type 2 diabetes mellitus and diabetic cardiomyopathy (DCM)." (PMID 34368154, 2021). "Many hepatic miRNAs located in the miR-379/miR-544 cluster were significantly increased in leptin-receptor-deficient type 2 mice (db/db), a mouse model of diabetes." (PMID 34527673, 2021). "In this study, we used a leptin receptor-deficient (db/db) mouse model, to investigate the effects of Azilsartan on diabetes-associated BBB permeability and the expression of tight junction protein occludin." (PMID 34266350, 2021). "The objective of the present study was to identify the association of the TNF-α- 308G/A and leptin receptor (LEPR) Gln223Arg polymorphisms with the risk of development of type 2 diabetes mellitus (T2DM)." (PMID 35052401, 2021). "The Zucker diabetic fatty rat includes a further mutation, which, in the context of the LepR mutation in this strain, accelerates the development of diabetes." (PMID 32326226, 2020). "We used young, leptin receptor deficient (Db/Db) mice to mimic the effect of diet and diabetes on adolescents." (PMID 32374776, 2020). "Next, we were interested in studying if the losses of mitochondrial and myelin lipids observed in db/db mice, where leptin receptor deficiency induces diabetes, also occurred in diet-induced obese mice." (PMID 33148881, 2020). "We used a special diet, Purina #5008, to induce diabetes in Zucker leptin receptor gene-deficient rats (fa/fa) to establish Zucker diabetic fatty (ZDF) rats, simulating the early stage of T2DM." (PMID 32817751, 2020). "It is noteworthy that db/db mice become obese due to hyperphagia induced by leptin receptor deficiency and diabetes develops in a highly strain-dependent manner secondary to genetic mutations poorly relevant in the human disease." (PMID 33066497, 2020). "Zucker diabetic fatty rats (ZDF) have a mutation within the leptin receptor that prevents downstream signaling following leptin binding." (PMID 32152264, 2020). "In conclusion, prediabetes/diabetes from leptin receptor deficiency resulted in cortical and trabecular bone changes and diminished torsional failure strength." (PMID 32374776, 2020). "For example: IGF1, IGF2 and LEPR, which have previously been associated with diabetes, while STAT5B and ROCK1 have shown weaker associations to the disease." (PMID 32735660, 2020). "Accumulation of improperly folded proinsulin and detection of ER stress response are early events in the development of diabetes in leptin receptor-deficient mice." (PMID 31184302, 2019). "The diabetes (db) gene encoded the leptin receptor (LEPR or OB-R), which exists in at least six isoforms (one soluble, four short and one long isoforms), differing in cytoplasmatic domain length." (PMID 31027158, 2019). "We isolated islets from newly onset diabetes leptin-receptor–deficient db/db mice, in which proinsulin synthesis is significantlyup-regulated to compensate severe insulin resistance." (PMID 31311313, 2019). "In genetically obese mice with otherwise wild-type islets, disulfide-linked complexes of proinsulin are more abundant, and leptin receptor-deficient mice, the further increase of such complexes tracks with the onset of islet insulin deficiency and diabetes." (PMID 31184302, 2019). "We conducted this study to explore the association of polymorphisms in LEPR with type 2 diabetes mellitus (T2DM) and its related metabolic traits." (PMID 29301582, 2018). "In previous studies, several single nucleotide polymorphisms (SNPs) of LEPR, such as rs1137101, rs1137100, rs6700896, and rs8179183, have been proven to be associated with a variety of chronic diseases (diabetes mellitus, hypertension, and some cancers)." (PMID 28368354, 2017).
diabetes (continued). "The Leptin receptor (LEPR) Gln223Arg gene polymorphism has been associated with an increased susceptibility to Type 2 diabetes mellitus (T2DM)." (PMID 28977915, 2017). "This study aimed to evaluate the validation of the leptin receptor-deficient mice model for secondary osteoporosis associated with type 2 diabetes mellitus (T2DM) at bone micro-architectural level." (PMID 27283954, 2016). "Streptozotocin (STZ)-induced diabetes is an extensively used mouse model for type 1 diabetes, whereas leptin or leptin receptor (Lepr)-deficient mice, ob/ob and db/db respectively, are frequently used as models of type 2 diabetes." (PMID 27188595, 2016). "Leptin receptor, which is encoded by the diabetes (db) gene and is highly expressed in the choroid plexus, regulatesenergy homeostasis, the balance between food intake and energy expenditure, fertility and bone mass." (PMID 26537785, 2015). "Since the phenotype of type 2 diabetes mellitus in the ZDF animal model is based on a homozygous mutation in the leptin receptor, our results can only be applied with restrictions to humans." (PMID 23497197, 2013). "The leptin receptor (ObR) is encoded by the diabetes gene (db) and alternative splicing of this gene generates six leptin receptor isoforms (ObRa-f) with identical N-terminal domains but vary in the length of their C-terminal region." (PMID 23964236, 2013). "Programming hepatic triglyceride storage also has consequence to glucose homeostasis as we found that a reduced capacity to store triglycerides in the liver is associated with more rapid and severe progression to diabetes in leptin receptor mutant mice." (PMID 24130751, 2013). "Further studies, which reveal nuclear receptor binding to specific response elements present in Slco promoters, will further elucidate how these transporters are regulated in leptin/leptin receptor deficient diabetes models." (PMID 22524730, 2012). "Leptin mediates its biological effects via activation of the leptin receptor (ObR) which is encoded by the diabetes (db) gene." (PMID 22254146, 2012). "db/db mice, a well defined type 2 diabetes mouse model with mutations in the leptin receptor gene was used to characterize the relationship between diabetes and WNV disease severity." (PMID 22953001, 2012). "Db/db mice (BKS.Cg-m +/+ Leprdb/J) mice possess a spontaneous diabetes (Db) mutation in the leptin receptor." (PMID 22524730, 2012). "As the leptin receptor is inactivated in db/db mice leptin cannot be directly impacting α-cell number, though it is indirectly influencing α-cell number by causing diabetes." (PMID 21283589, 2011). "On employing a candidate gene approach to the association study of CNVs with diabetes and metabolic traits, we targeted the genomic locus of the LEPR gene encompassing approximately 200 kb of chromosome 1." (PMID 20624279, 2010). "Previously, we have demonstrated that the C57BLK db/db (db/db) mouse, a model of type 2 diabetes that carries the loss-of-function leptin receptor mutant, develops mechanical allodynia in the hind paws during the early stage (6-12 wk of age) of diabetes." (PMID 20482876, 2010). "Recent observations in leptin receptor-overexpressing obese db/db mice showed suppressed SREBP1c and adipogenic gene-expression levels, severe diabetes and beta cell loss 6 weeks before the db/db controls." (PMID 19787047, 2009). "The db/db mouse is a well established model of diabetes that contains a homozygous mutation in the leptin receptor gene." (PMID 19589179, 2009). "Although the db/db mouse model has been extensively used as a type 2 diabetic animal model, there is still debate for using db/db mouse as type 2 diabetic animal model due to relevance of leptin receptor deficiency and the severity of phenotype representative of late-stage diabetes." (PMID 40640841, 2025).
diabetes (continued). "In this study, leptin receptor mutant mice (db/db mice) served as a murine model of DPN to explore the underlying mechanisms responsible for therapeutic effect of inulin on DPN across diverse stages of diabetes." (PMID 41264657, 2025). "Additionally, these LEPR polymorphisms have been associated with diabetes, insulin resistance, and metabolic syndrome." (PMID 40551902, 2025). "In a previous work of our group, a higher level of leptin was observed in individuals with youth-onset diabetes in Bangladesh, reflecting a leptin resistance that may be related to LEPR polymorphism." (PMID 40551902, 2025). "While the monogenic ZDF rodent model rapidly develops diabetes by 8 weeks of age due to a missense mutation in their leptin receptor, the ZDSD rat overcomes this by exhibiting normal leptin signaling and likely has polygenetic contributions to the development of diabetes." (PMID 37233701, 2023). "Leptin receptor (Lepr) encoded by the diabetes (db) gene is highly expressed in the choroid plexus." (PMID 35269691, 2022). "The severity of the induced diabetes in monogenic rodent models—such as leptin-deficient ob/ob and leptin receptor-deficient db/db mouse models, KK-Ay mice, and Otzhka Long-Evans Tokushima Fatty (OLETF) rats—is strongly affected by the strain’s genetic background." (PMID 36232867, 2022). "Leptin receptor-deficient db/db mice are a widely used preclinical model in diabetes research." (PMID 35126811, 2022). "We used three independent models of diabetes—leptin receptor–deficient mice (db/db), high-fat diet (HFD)–induced disease, and STZ-induced disease (two models of type 2 diabetes and one type 1 model)—that are all associated with progressive retinal dysfunction and dysmorphology." (PMID 34425110, 2021). "The obese ZSF1 rat is a genetic model of diabetes that possesses two mutations of the leptin receptor and it may prove more difficult to ameliorate glucose utilization with HIF-PHIs in this model." (PMID 34339435, 2021). "Additionally, in the livers derived from Lepr db/db (homozygous for the diabetes db mutation of the leptin receptor) mice, the expression of 156 miRNAs was altered when compared to healthy controls." (PMID 32545342, 2020). "The leptin receptor (Ob-R) is encoded by the diabetes (db) gene." (PMID 28819795, 2019). "Furthermore, our finding of LV hyperdynamic contractility early in the course of diabetes mellitus is in agreement with results from animal model studies in leptin receptor-deficient mice utilizing in vivo catheterization." (PMID 26839891, 2016). "Moreover, acute LepR deficiency is an excellent model for future studies to interrogate the signals regulating beta cell growth for the development of potential diabetes therapies." (PMID 27003683, 2016). "One limitation of this study was the sole use of the leptin-receptor-deficient model of diabetes." (PMID 24057002, 2013). "To identify diabetes associated changes in skin physiology and tissue repair, we have compared the whole transcriptome of non‐injured skin and full‐thickness skin wounds of the leptin receptor deficient db/db diabetes mouse model with age matched healthy wild‐type littermate control mice." (PMID 41051359, 2025). "In addition, some studies showed that the (A) allele of LEPR Gln223Arg gene polymorphism might be associated with type 2 diabetes mellitus (T2DM)." (PMID 37662867, 2023). "The two studies employed genetically modified mice: db/db mice and ob/ob mice respectively, both commonly used animal models in diabetes research based on leptin or leptin receptor gene modifications." (PMID 40386230, 2025). "LEPR, on the other hand, is a leptin receptor that has been found to play an important role in cardiac hypertrophy, heart failure, and diabetes mellitus." (PMID 40313483, 2025). "We demonstrated that scutellarin (SCU) effectively mitigated bone loss in DOP mice, and co‐treatment with SCU significantly reduced diabetes‐induced senescence in LepR+MSCs." (PMID 39668494, 2025).
diabetes (continued). "To further validate these findings in vivo, we utilised a LepRcre‐tdTomato mouse diabetes model, created by crossing the LepR‐Cre strain with the Rosa‐LSL‐tdTomato strain." (PMID 39668494, 2025). "Our results demonstrate that SCU mitigates the senescence of LepR+ MSCs induced by diabetes by upregulating Nrf2 at the posttranslational level." (PMID 39668494, 2025). "As GLIS3 plays a critical role in pancreatic beta cells and diabetes, we examined this possibility in pancreatic islets from wild-type mice and mice with a genetic disruption of the leptin receptor (db/db), which leads to a diabetic phenotype." (PMID 41369402, 2025). "First, although single-nucleotide polymorphism of LEPR was reported to be associated with T2DM 79, per CDC most T2DM humans fell sick mainly due to their diets, instead of their genetics (CDC diabetes statistics)." (PMID 39484619, 2024). "LEPR rs7799039 is a nucleotide variant located in the promoter region of the LEPR gene, and it has been associated with a higher risk of GWG and type 2 diabetes mellitus development." (PMID 38474283, 2024). "Given its involvement in type 2 diabetes mellitus, the LEPR gene is frequently related to type 2 diabetes." (PMID 38198642, 2023). "The db/db mouse model derived from the C57BL/6J mice has a defective leptin receptor gene with the characteristic of spontaneous diabetes mellitus 2 development." (PMID 37124208, 2023). "LepR−/− rats are obese as early as 4 weeks of age with severe type 2 diabetes mellitus developing in the animals by 21 weeks of age30, thus closely mimicking the disease environment of chronic metabolic syndrome." (PMID 37730735, 2023). "Leptin exerts its function by binding to the leptin receptor (Ob-R), a product of the diabetes (db) gene." (PMID 36551211, 2022). "Type 2 DM mice (C57BLKS/J Lepr (db)/Lepr (db) mice and BKS.Cg-m+/+Lepr(db)/J mice) were used to investigate LEPR effects on cardiomyocyte function and ventricular arrhythmias after MI and after developing diabetes." (PMID 35845045, 2022). "Inline, sRANKL was correlated with markers of metabolic dysregulation, such as pre-existing diabetes and various adipokines (e.g., adiponectin, leptin receptor)." (PMID 35054232, 2021). "Due to the recessive leptin receptor gene defect on the autosome, short-chain leptin receptor Ob/Ra replaced long-chain leptin receptor Ob/Rb, leading to spontaneous diabetes." (PMID 34691233, 2021). "In our study, the diabetes condition in leptin receptor knockout mice was confirmed by measuring the fasting blood glucose levels." (PMID 32024487, 2020). "Leptin receptors are produced by the diabetes (db) gene and six isoforms of the leptin receptor, ObRa-f, exist." (PMID 30386207, 2018). "This adipokine exerts its physiological activity through its receptor (LEPR or Ob-R), a class I cytokine receptor family from diabetes (db) gene (Münzberg and Morrison, 2015)." (PMID 29910742, 2018). "In the group of men suffering from diabetes, in the untreated subjects, the plasma concentration of leptin receptor was remarkably lower when compared to the concentrations observed both in the group of healthy and diabetic men after applying the therapy." (PMID 28758947, 2017). "Given the profound diabetes observed in leptin receptor-deficient mice (db/db), and leptin being an important hyperglycemic factor in tilapia, it is very tempting to speculate that leptin receptor deficiency in zebrafish would have an effect on glucose homeostasis." (PMID 28303116, 2017). "The concentration of leptin receptor in individuals with diabetes before treatment was remarkably lower than in healthy individuals." (PMID 28758947, 2017). "Leptin receptor antagonism would be a promising approach for reversing diabetic bone marrow mobilopathy." (PMID 27188595, 2016). "More studies in larger cohort and functional analyses of LEPR are required to reinforce the results and elucidate its biological roles in diabetes." (PMID 27195302, 2016).